H2BC11 (H2B clustered histone 11)
Description:
Core component of nucleosome. Nucleosomes wrap and compact DNA into chromatin, limiting DNA accessibility to the cellular machineries which require DNA as a template. Histones thereby play a central role in transcription regulation, DNA repair, DNA replication and chromosomal stability. DNA accessibility is regulated via a complex set of post-translational modifications of histones, also called histone code, and nucleosome remodeling. Has broad antibacterial activity. May contribute to the formation of the functional antimicrobial barrier of the colonic epithelium, and to the bactericidal activity of amniotic fluid.
Synonyms: H2B/r; H2BFR; HIST1H2BJ; H2BJ
Tractability: Small molecule: a structure with a bound ligand is known. Antibody: its Gene Ontology location is reachable by antibodies, with high confidence. PROTAC: UniProt records ubiquitination sites on it; ubiquitination databases record sites on it.
Gene: Protein-coding gene on chromosome 6 (27,122,657 to 27,132,795, reverse strand). Ensembl gene ENSG00000124635.
Subcellular location: Nucleus; Chromosome
Subcellular location (Human Protein Atlas): Nucleoplasm; Cytosol
Pathways (Reactome):
Gene expression (Transcription): B-WICH complex positively regulates rRNA expression; DNA methylation; ERCC6 (CSB) and EHMT2 (G9a) positively regulate rRNA expression; MLL4 and MLL3 complexes regulate expression of PPARG target genes in adipogenesis and hepatic steatosis; NoRC negatively regulates rRNA expression; PRC2 methylates histones and DNA; RNA Polymerase I Promoter Escape; RNA Polymerase I Promoter Opening; RUNX1 regulates genes involved in megakaryocyte differentiation and platelet function; RUNX1 regulates transcription of genes involved in differentiation of HSCs; Regulation of endogenous retroelements by KRAB-ZFP proteins; Regulation of endogenous retroelements by Piwi-interacting RNAs (piRNAs); Regulation of endogenous retroelements by the Human Silencing Hub (HUSH) complex; SIRT1 negatively regulates rRNA expression; Transcriptional regulation by small RNAs
Chromatin organization: CHD1 and CHD2 subfamily; CHD6, CHD7, CHD8, CHD9 subfamily; ChAHP complex assembly; HATs acetylate histones; HDACs deacetylate histones; Interaction of NuRD complexes with transcription factors; NuRD complex assembly
DNA Repair: Cleavage of the damaged purine; Cleavage of the damaged pyrimidine; Nonhomologous End-Joining (NHEJ); Processing of DNA double-strand break ends; Recognition and association of DNA glycosylase with site containing an affected purine; Recognition and association of DNA glycosylase with site containing an affected pyrimidine; Recruitment and ATM-mediated phosphorylation of repair and signaling proteins at DNA double strand breaks
Cell Cycle: Condensation of Prophase Chromosomes; Deposition of new CENPA-containing nucleosomes at the centromere; G2/M DNA damage checkpoint; Inhibition of DNA recombination at telomere; Packaging Of Telomere Ends
Developmental Biology: Activation of anterior HOX genes in hindbrain development during early embryogenesis; Chromatin modifications during the maternal to zygotic transition (MZT); Replacement of protamines by nucleosomes in the male pronucleus; Transcriptional regulation of granulopoiesis
Disease: Defective pyroptosis; Dengue Virus-Host Interactions
and 18 more pathways
Gene Ontology:
Molecular function: lipopolysaccharide binding; protein binding; structural constituent of chromatin; DNA binding; protein heterodimerization activity
Biological process: antibacterial humoral response; antimicrobial humoral immune response mediated by antimicrobial peptide; defense response to Gram-negative bacterium; defense response to Gram-positive bacterium; innate immune response in mucosa; killing of cells of another organism; negative regulation of tumor necrosis factor-mediated signaling pathway; chromatin organization; nucleosome assembly; protein localization to CENP-A containing chromatin
Cellular component: CENP-A containing nucleosome; extracellular region; nucleosome; nucleus; plasma membrane; nucleoplasm; chromosome
Genetic constraint (gnomAD): Loss-of-function variants: 7 observed, 6.34 expected, observed/expected ratio (o/e) 1.1, 90% interval 0.62 to 1.82. That is too few expected variants to judge how well the gene tolerates losing a copy. Missense variants: 215 observed, 178.38 expected, observed/expected ratio (o/e) 1.21, 90% interval 1.08 to 1.35. Synonymous variants: 127 observed, 74.66 expected, observed/expected ratio (o/e) 1.7, 90% interval 1.47 to 1.93.
Homologues: Orthologues: chimpanzee H2BC11 (100% identical), macaque H2BC11 (100% identical), pig H2BC11 (100% identical), mouse H2bc21 (98% identical), tropical clawed frog h2bc11 (94% identical), tropical clawed frog h2bc21 (93% identical). Paralogues in human: H2BC12 (99% identical), H2BC21 (99% identical), H2BC10 (98% identical), H2BC17 (98% identical), H2BC4 (98% identical), H2BC6 (98% identical), H2BC7 (98% identical), H2BC8 (98% identical), H2BC12L (98% identical), H2BC15 (98% identical), H2BC3 (98% identical), H2BC5 (98% identical), and 9 more.
Diseases named in the same sentence as H2BC11 in open-access papers:
H2BC11 is named in the same sentence as 15 diseases in open-access papers, as found by Europe PMC text mining. Sharing a sentence is not in itself a finding about the gene and the disease. The quoted sentences say what the papers report.
glioma (3 papers, 2021 to 2023). A benign or malignant brain and spinal cord tumor that arises from glial cells (astrocytes, oligodendrocytes, ependymal cells). "In particular, high H2BC5, H2BC9, H2BC11, and H2BC21 expression was associated with poor glioma prognosis." (PMID 36387186, 2022). "This study used multiple algorithms to assess the correlation between H2B gene expression and immune cell infiltration and found that H2B family genes, especially H2BC9 and H2BC11 are closely related to the immune system of glioma patients." (PMID 36387186, 2022). "Univariate and multivariate Cox analysis showed that H2BC5, H2BC9, H2BC11, and H2BC21 are high-risk factors for glioma." (PMID 36387186, 2022). "First, we used the ssGSEA algorithm to assess immune cell infiltration in gliomas and found that H2BC9 and H2BC11 were positively correlated with influx of macrophages, Th2 cells, neutrophils and eosinophils." (PMID 36387186, 2022). "Several studies have shown that H2BC5, H2BC9, and H2BC11 are independent prognostic factors of cervical cancer, and H2BC12 is an independent prognostic factor for low-grade glioma." (PMID 36387186, 2022). "Enrichment analysis of H2BC5, H2BC9, H2BC11, and H2BC21 was also conducted to understand how the H2B gene is involved in the pathological progression of glioma." (PMID 36387186, 2022). "Kaplan-Meier survival analysis showed that high expression of H2BC5, H2BC9, H2BC11, and H2BC21 correlated with a poor OS, DFS, and PFI of glioma patients." (PMID 36387186, 2022). "The methylation status of H2BC5, H2BC9, H2BC11, and H2BC21 in different glioma cohorts was evaluated in the Methsurv database." (PMID 36387186, 2022). "Besides, The algorithm of the estimate package showed that the expression of H2B family genes, especially H2BC9, H2BC11 and H2BC12 was positively correlated with the presence of stromal cells in glioma, the level of immune cells and the purity of tumor cells." (PMID 36387186, 2022). "In summary, H2BC5, H2BC9, H2BC11, and H2BC21 were independent prognostic indicators of glioma, and H2BC9 and H2BC11 may correlate with tumor immunity." (PMID 36387186, 2022). "Expression of H2BC5, H2BC9, H2BC11, and H2BC21 was higher in glioma tissues." (PMID 36387186, 2022). "Collectively, these data indicated that H2BC5, H2BC9, H2BC11, and H2BC21 could independently predict glioma prognosis." (PMID 36387186, 2022). "The analysis of H2B family gene expression in glioma showed that H2BC5, H2BC9, H2BC11, and H2BC21 can be used as independent predictive factors for glioma prognosis, and overexpression of H2BC9 and H2BC11 may lead to tumor deterioration through the immune system." (PMID 36387186, 2022). "Moreover, the ROC curve showed that H2BC5, H2BC9, H2BC11, and H2BC21 all had meaningful predictive power for glioma, especially H2BC9 and H2BC11, which showed excellent sensitivity and specificity in predicting the survival of glioma patients, with an area under the curve (AUC) of >0.8." (PMID 36387186, 2022).
breast carcinoma (1 paper, 2025). "Conversely, hub genes such as H2BC11, MX1, OAS2, and IFIT3 displayed greater expression in more aggressive breast cancer subtypes." (PMID 41009689, 2025).
infertile (1 paper, 2023). "In fact, we have observed increased retention of histone proteins (H1-3, H1-4, H1-7, H2BC19P, H2BC11, H2BC12, H2BS1) in the spermatozoa of idiopathic infertile patients implying improper nuclear remodelling." (PMID 37261076, 2023).
viral infections (1 paper, 2021). "Studies have reported that H2BC11 is associated with interferon signaling during viral infections." (PMID 34917088, 2021).
tumor (1 paper, 2022). "On the other hand, H2BC9 and H2BC11 were inversely associated with pDC cells, which promoted the recruitment of regulatory T cells into the tumor microenvironment and resulted in immunosuppression and tumor growth." (PMID 36387186, 2022). "H2BC9 and H2BC11 positively correlate with the immune checkpoint PDCD1, which mediates inhibitory pathways that are exploited by tumors to mitigate antitumor immunity and escape destruction by the immune system, thereby promoting tumor survival." (PMID 36387186, 2022).
H2BC11 also shares sentences with these, for which no sentence is quoted: cancer (2 papers); cervical cancer (2); autoimmune disorders (1); COVID-19 (1); infection (1); lung adenocarcinoma (1); neurodegenerative disease (1); rheumatoid arthritis (1); skin cutaneous melanoma (1); systemic lupus erythematosus (1).